BMS1P2 (BMS1 pseudogene 2)
Synonyms: bA144G6.1; OTTHUMG00000018113; bA302K17.2; OTTHUMG00000018142; formerly BMS1LP2; BMS1P6; BMS1LP6
Gene: Transcribed unprocessed pseudogene on chromosome 10 (47,540,077 to 47,551,919, reverse strand). Ensembl gene ENSG00000251079.
Diseases named in the same sentence as BMS1P2 in open-access papers:
BMS1P2 is named in the same sentence as 1 disease in open-access papers, as found by Europe PMC text mining. Sharing a sentence is not in itself a finding about the gene and the disease.
BMS1P2 shares sentences with these, for which no sentence is quoted: Esotropia (1 paper).